HMGB1 (high mobility group box 1)
Diseases named in the same sentence as HMGB1 in open-access papers (continued):
Sharing a sentence is not in itself a finding about the gene and the disease.
breast carcinoma (continued). "Similarly, plasma HMGB1 levels were significantly higher in patients with breast cancer who were sensitive to epirubicin/docetaxel than in non-responders." (PMID 38725632, 2024). "Furthermore, the risk of metastatic relapse was notably higher in patients with ASMA + high/HMGB1 low in non-inflammatory breast cancer samples." (PMID 39830522, 2024). "Immunohistochemistry examination of breast cancer tumors from patients treated with adjuvant anthracycline showed that tumors with no nuclear HMGB1 staining in the majority of their cells were significantly associated with a negative impact on overall and progression-free survival." (PMID 34497771, 2021). "However, although another group of patients with breast cancer undergoing NAC had increased levels of CRT as well as HMGB1, neither increase correlated significantly with pathological effects or survival." (PMID 34638242, 2021). "In overcoming P-glycoprotein (P-gp)-expressing doxorubicin resistance in breast cancer cells, the clinically approved P-gp inhibitor tariquidar and its derivatives restored doxorubicin accumulation and enhanced ICD, defined as an increase in CRT translocation and the release of HMGB1 and ATP." (PMID 34638242, 2021). "The combination of NKT cell activation with chemotherapy, e.g., gemcitabine or cyclophosphamide (currently used in BC treatment), enhanced the immunogenicity of breast tumor cells by increasing ICD signals (CRT, ATP, HMGB1) in metastatic breast cancer." (PMID 34885109, 2021). "In the present study, although the 4T1 mouse mammary carcinoma cells are known to be poorly immunogenic, Nano-DOX was still found, both in vitro and in vivo, to elicit marked emission of three out of four typical DAMPs, i.e. HSP90, CRT and ATP, only leaving HMGB1 unchanged." (PMID 31623629, 2019). "Although the pathways activated by extracellular HMGB1 in breast cancer cells have not been identified, they may lead to the induction of cancer progression and drug resistance." (PMID 25512109, 2014). "In breast cancer tissues investigated by immunohistochemistry, it is possible that phosphorylated HMGB1 may reside in the cytoplasm which corresponds to our observations of increased cytoplasmic HMGB1 in breast cancer tissues (data not shown)." (PMID 25512109, 2014). "Given the role of the CXCR4/CXCL12 axis in breast cancer metastatic spread, and the differences observed between MDA-MB-231 and MCF-7 cells, our data point to initial stages of breast cancer as possible models where targeting the CXCL12/HMGB1 heterocomplex could be particularly promising." (PMID 38803493, 2024). "We selected for further assessment HMGB1, a multifunctional protein that for might be involved in tumor progression and drug resistance through by-pass signaling, and has also been reported to be related to the recurrence free survival (RFS) of patients with breast cancer." (PMID 34182538, 2021). "However, the viability of breast cancer cells could not be completely rescued by an HMGB1 neutralizing antibody, implying that other substances released from dead cancer cells may be responsible for Dox resistance." (PMID 25512109, 2014). "The suppression of HMGB1 and RAGE expressions in breast cancer revealed the impaired invasion capability without affecting cell proliferation, however, this unclear mechanism controlling this effect needs to be investigated." (PMID 35610613, 2022). "In addition, many cancer cells, including breast cancer cells of MDA-MB-231, are capable of cytoplasmic translocation of HMGB1 by the PTMs in the absence of external stimuli." (PMID 40389855, 2025). "Interestingly, the MDA-MB-231-LM3 breast cancer TuNEPs exhibited a group of RAGE agonists, including HMGB1 and HMGB2, which were absent in PC9 lung cancer TuNEPs." (PMID 40751052, 2025). "In addition, the possible ferroptosis mechanisms of CDKN2A, PSAT1, SLC7A11, LAMP2, CAV1, and HMGB1 in TNBC and ASNS, ZFP69B, ELAVL1, TF, HELLS, and DPP4 in breast cancer have not been reported." (PMID 36568247, 2022).
breast carcinoma (continued). "High-mobility group box 1 (HMGB1) is a non-histone chromatin-binding protein that exists widely in the nucleus and cytoplasm, which has been proven to up-regulate Treg cells and M2 macrophages in basal-like breast cancer cells." (PMID 34717710, 2021).
Stroke (179 papers, 2010 to 2025). Sudden impairment of blood flow to a part of the brain due to occlusion or rupture of an artery to the brain. "Hyperglycemia and hypertension are risk factors for stroke, and the role played by HMGB1 in hemorrhagic transformation after rtPA thrombolysis needs to be further elucidated." (PMID 38740617, 2025). "Recently, it has been found that higher HMGB1 levels in the acute phase of ischemic stroke are also associated with an increased risk of post-stroke depression and stroke-related pneumonia." (PMID 38740617, 2025). "As a systemic inflammatory factor, HMGB1 is also implicated in post-stroke depression and an elevated risk of stroke-associated pneumonia." (PMID 38740617, 2025). "The results of this study suggest that elevated early serum HMGB1 levels are associated with an increased risk of cognitive decline after stroke, which has important implications for future research." (PMID 38708343, 2024). "Future studies should also consider exploring the predictive value of HMGB1 in combination with other biomarkers and clinical factors to develop more accurate risk stratification models for post-stroke cognitive impairment." (PMID 38708343, 2024). "This study helps address major gaps in prognostic biomarkers to identify stroke patients at risk of dementia and provides a rationale for targeting HMGB1 therapeutically to prevent post-stroke cognitive decline." (PMID 38708343, 2024). "High mobility group box 1 (HMGB1) is a protein released by ischemic neurons and implicated in inflammation after stroke." (PMID 38708343, 2024). "Several previous studies have described associations between circulating HMGB1 levels measured during the initial days to weeks following a cerebrovascular accident and the subsequent emergence of cognitive impairments." (PMID 38708343, 2024). "Despite emerging evidence linking early elevated HMGB1 levels with the risk of post-stroke cognitive dysfunction, most prior studies had small sample sizes and measured HMGB1 beyond the initial 24-hour period when neuroinflammatory processes rapidly escalated." (PMID 38708343, 2024). "(2022) discovered that HMGB1 concentrations assessed at the 72-hour mark post-stroke were associated with performance on the Mini-Mental State Exam (MMSE) administered 3 months later in a cohort of 56 individuals who had experienced a cerebrovascular event." (PMID 38708343, 2024). "Several inflammatory markers are elevated granulocytes and monocytes, epinephrine, high-mobility group protein B1 (HMGB-1), and CD11b implicated in developing stroke or seizures." (PMID 36338344, 2022). "To further establish a causal role for HMGB1 in mediating NET formation after stroke, we treated thrombocytopenic mice with recombinant HMGB1 (rHMGB1)." (PMID 35358095, 2022). "In some life‐threatening diseases, HMGB1 levels are remarkably high and associated with acute inflammation, such as stroke and acute myocardial infarction." (PMID 35765707, 2022). "Mechanistically, platelets were identified as the critical source of HMGB1 that caused NETs in the acute phase of stroke." (PMID 35358095, 2022). "In particular, patients with higher levels of HMGB-1 had a higher risk of myocardial infarction, stroke and death from cardiovascular diseases." (PMID 36244983, 2022). "HMGB1 was also found in the serum of stroke patients and high levels were linked to a worse outcome, indicated by higher follow-up modified Rankin scores at 1 year." (PMID 34966269, 2021). "In fact, we demonstrate that high levels of HMGB1 are associated with the presence of unstable plaque and a more frequent history of stroke." (PMID 34044825, 2021). "We here analyzed associated HMGB1 expression in human thromboemboli retrieved via mechanical thrombectomy from 37 stroke patients with large vessel occlusion." (PMID 34681935, 2021).
Stroke (continued). "After stroke, cytoplasmic translocation and the release of HMGB1 would stimulate neurocyte and cause severe inflammatory response through signalling and molecular transport mechanisms." (PMID 34231932, 2021). "The increase in PARP1, MMP9 and HMGB1 associated with stroke in SHRs points to the unique relationship between hypertension and the enhancement of post-stroke cell death." (PMID 33214598, 2020). "Although increasing numbers of studies have investigated the associations of variants in the HMGB1/RAGE axis with susceptibility to stroke, the results have been inconsistent." (PMID 29245967, 2017). "In the ischemic injury models, MMP9 activity was detected in endothelial cells, astrocytes, and neurons, and HMGB1 released during stroke was implicated in activation of MMP9 via TLR4 signaling." (PMID 25879213, 2015). "We have recently shown that RAGE-deficient mice were protected from ischemic stroke and HMGB1 promotes stroke-induced neuronal cell death by activating signalling cascades associated with RAGE and TLR activation." (PMID 25886362, 2015). "Lastly, we demonstrated that stroke-induced lymphopenia is associated with a reduction in HMGB1 release in the peripheral blood." (PMID 23555048, 2013). "Moreover, signaling pathways such as HMGB1–RAGE contribute to post-stroke immunosuppression and heightened susceptibility to stroke-associated pneumonia." (PMID 41463120, 2025). "ROS oxidized low-density lipoprotein (OxLDL), a risk factor for stroke, stimulates oxidative stress-induced secretion of HMGB1 in macrophages, and HMGB1 promotes macrophage-derived foam cell formation via the endoplasmic reticulum stress (ERS)/C/EBP-homologous protein (CHOP) pathway." (PMID 38740617, 2025). "Our study revealed a strong association between HMGB1 expression and stroke incidence." (PMID 40128654, 2025). "High mobility group box 1 (HMGB1) has been identified as a crucial player in orchestrating detrimental inflammatory responses in various acute cerebral insults, including stroke, and has also been implicated in the pathogenesis of several neurodegenerative disorders." (PMID 38708343, 2024). "Whether very early HMGB1 levels are associated with later development of post-stroke cognitive impairment requires further investigation." (PMID 38708343, 2024). "Even in the fully adjusted Model 3, which accounted for the covariates incorporated in Model 2 as well as HMGB1 levels, elevated circulating HMGB1 retained its status as an independent risk predictor for post-stroke cognitive impairment (regression coefficient = 0.236, p < 0.001)." (PMID 38708343, 2024). "We hypothesized that acute elevations in systemic HMGB1 would independently predict the risk of post-stroke cognitive decline even after accounting for potential confounding factors." (PMID 38708343, 2024). "Our analyses unveiled a distinct linear trend, wherein the risk of developing post-stroke cognitive impairment escalated in lockstep with higher baseline circulating HMGB1 levels across the defined quartile strata among acute ischemic stroke patients (p < 0.001)." (PMID 38708343, 2024). "Additionally, mechanistic studies are needed to elucidate the underlying biological pathways linking HMGB1 to the development of cognitive impairment following stroke." (PMID 38708343, 2024). "In Italian diabetes mellitus patients, HMGB1 levels were related with an increased risk of carotid-plaque vulnerability, which may result in stroke occurrence." (PMID 36421903, 2022). "Moreover, a recent study showed that higher baseline levels of HMGB1 were related to increased risk of post-stroke depression." (PMID 36421903, 2022). "Moreover, the reduction of plasma HMGB1 in thrombocytopenic mice was associated with a significant reduction in plasma MPO-DNA complexes 24 hours after stroke (136% ± 53.1% vs. 295.6% ± 128.1%)." (PMID 35358095, 2022).
Stroke (continued). "In addition, platelets and leukocytes are another important source of damage-associated molecular patterns (DAMPs) such as HMGB1, which has been largely neglected in the stroke field." (PMID 34681935, 2021). "In addition, the pro-inflammatory danger-associated molecular pattern (DAMP) High-Mobility-Group-Protein B1 (HMGB-1) is thought to play an important role in the modulation of post-stroke immune alterations." (PMID 32581999, 2020). "Furthermore, glycyrrhizin administration reduced neuroinflammation by inhibiting the activity of macrophages and neutrophils associated with HMGB1 release from the ischemic brain after stroke." (PMID 33384585, 2020). "To explore whether the effects of RAGE and HMGB1 gene variants are confined to a specific subtype or related to overall risk, we further separated the IS patient groups into stroke subgroups based on the CISS system." (PMID 29245967, 2017). "These lines of evidence and our findings collectively indicate that variants in the HMGB1/RAGE axis may play protective roles in stroke development." (PMID 29245967, 2017). "Indeed, we found that PBMC numbers were increased in rats with splenectomy after stroke, and this is associated with less HMGB1 release in the blood." (PMID 23555048, 2013). "HMGB1 acts as a proinflammatory cytokine, and may play a role in the progression of risk factors of stroke, such as HT, HL, DM, atherosclerosis, and thrombosis." (PMID 24065095, 2013). "Furthermore, our data suggests that HMGB1 is associated with T cell-mediated lymphopenia after stroke." (PMID 23555048, 2013). "Extracellular HMGB1 causes multiple organ failure and contributes to the pathogenesis of hypertension, hyperlipidemia, diabetes mellitus, atherosclerosis, thrombosis, and stroke." (PMID 24065095, 2013). "In addition, a recent study have shown that oxygenized low density lipoprotein (OxLDL), a risk factor of stroke, stimulates HMGB-1 secretion in macrophages resulted from oxidative stress, then HMGB1 can contribute to macrophage-derived foam cells formation via ERS/CHOP pathway." (PMID 31001089, 2019). "In addition, HMGB1 (HMGB1 signaling) codes a proinflammatory cytokine, which is critical to the cell response to stress and is implicated in diseases characterized by cell damages and death (e.g., Alzheimer's disease, stroke, cancer)." (PMID 31134135, 2019). "Stroke-induced inflammation and the activation of proinflammatory mediators have been the focus of recent research into the mechanisms of stroke-induced brain damage, and high-mobility group box 1 protein (HMGB1), a typical damage-associated protein, has gained particular interest." (PMID 31001089, 2019). "Inhibition of the HMGB1/RAGE axis may be an effective treatment for these risk factors of stroke." (PMID 24065095, 2013). "However, based on these findings, the HMGB1/RAGE axis could be a potential therapeutic target of risk factors of stroke, including HT, HL, DM, atherosclerosis, and thrombosis." (PMID 24065095, 2013). "After a stroke or other stressful injury, active secretion of HMGB1 was observed in activated monocyte macrophages, vascular endothelial cells, fibroblasts, NK cells, and glial cells." (PMID 38740617, 2025). "During the delayed phase, HMGB1 plays a beneficial role in stroke through TLR receptors possibly by regulating proliferation and differentiation of neural stem progenitor cells and migration of oligodendrocytes." (PMID 38740617, 2025). "Elevated HMGB1 levels during the acute stroke phase correlate with worse outcomes by enhancing NET formation and recruitment, leading to neurofunctional deficits." (PMID 40290435, 2025). "Platelets are also an essential source of active HMGB1 secretion, and HMGB1 is critical in the acute phase of stroke to produce neutrophil extracellular traps(NETs) that exacerbate worsening post-stroke outcomes." (PMID 38740617, 2025).
Stroke (continued). "MALAT1 was proven to act as a competing endogenous RNA (ceRNA) to facilitate the berberine-mediated inhibition of HMGB1 by sponging miR-181c-5p in post-stroke inflammation." (PMID 39859155, 2025). "HMGB1 release includes passive release in early post-stroke cell necrosis and active secretion in the late phase of stroke." (PMID 38740617, 2025). "Our previous research demonstrated that HMGB1 induces NETosis in a stroke model utilizing permanent middle cerebral artery occlusion (MCAO) induced by the suture method." (PMID 39910417, 2025). "Conversely, in the late acute, subacute, and chronic phases (>3 weeks post-stroke), HMGB1 contributes to vascular remodeling and neurofunctional recovery." (PMID 40066310, 2025). "CD36 and scavenger receptor A mediate microglia internalization, but the unexplored pathways by which activated microglia mediate HMGB1 clearance and suppression of immune responses in stroke require attention." (PMID 38740617, 2025). "HMGB1 was significantly increased in plasma after tPA treatment in stroke patients, promoting the release of MMP9, and leading to blood–brain barrier disruption and hemorrhagic transformation." (PMID 38740617, 2025). "After stroke, the injured brain releases large amounts of HMGB1, which activates the RAGE and TLR4 pathways, transmitting danger signals to surrounding tissues." (PMID 41050264, 2025). "High-mobility group box-1 (HMGB1) is highly expressed in both neuronal cell bodies and axons and has been found to have late proinflammatory effects; thus, the role of HMGB1 in stroke has recently become a hot research topic in critical care medicine." (PMID 40128654, 2025). "It has been shown that stroke-induced up-regulation of monocyte hexokinase 2 (Hk2) depends on HMGB1, thus mediating vascular inflammation and atherosclerosis progression after stroke." (PMID 38740617, 2025). "The MALAT1/miR-181c-5p/HMGB1 axis has been identified as a novel key pathway in stroke inflammation." (PMID 39859155, 2025). "In the hyperacute and acute phases (within 4–5 days post-stroke), HMGB1 functions as a pro-inflammatory mediator, exacerbating neuronal death and blood–brain barrier disruption." (PMID 40066310, 2025). "Melatonin and the neuropeptide PNX-14 inhibited microglia activation-mediated inflammation after stroke by suppressing the high expression and release of HMGB1 and modulating the subsequent activation of the TLR4/MyD88/NF-κB signaling pathway." (PMID 38740617, 2025). "In conclusion, this study provides a novel perspective on the role of BCP in regulating HMGB1 expression and inflammation, demonstrating its potential for application in stroke treatment." (PMID 40128654, 2025). "Although there are multiple receptors for HMGB1, post-stroke HMGB1 receptor studies have centered around Toll-like receptors (TLR-2 and TLR-4) and the receptor for advanced glycosylation end products (RAGE)." (PMID 38740617, 2025). "In stroke patients, serum HMGB1 increased after thrombolytic-induced reperfusion, with serum concentration increasing as infarct size increases." (PMID 40406124, 2025). "The involvement of HMGB1 in the autophagy process of microglia in stroke and as an immune target for therapeutic purposes needs to be further investigated." (PMID 38740617, 2025). "HMGB1 contributes to the pathogenesis of multiple CNS disorders through its role in neurotoxicity, including traumatic brain injury, stroke, and multiple sclerosis." (PMID 41009351, 2025). "While OGD/HIBD studies focus on immediate cell death pathways, HAHH reveals how chronic microglial inflammation (via HMGB1-RAGE) drives progressive cognitive impairment—a process more relevant to altitude-related neurodegeneration than stroke." (PMID 41009351, 2025). "The expression of HMGB1 was elevated in the ipsilateral hemisphere 7 days after stroke induction compared to in the contralateral hemisphere (p < 0.05) and compared to the 6 h and 3 d groups (p < 0.01 and p < 0.05, respectively)." (PMID 40332314, 2025).